MRPS22 (mitochondrial ribosomal protein S22)
Synonyms: MRP-S22; C3orf5; RPMS22; GK002; GIBT; mS22; COXPD5; ODG7
Tractability: Small molecule: a structure with a bound ligand is known. PROTAC: ubiquitination databases record sites on it; its protein half-life has been measured.
Target class: Other cytosolic protein
Gene: Protein-coding gene on chromosome 3 (139,005,806 to 139,360,497, forward strand). Ensembl gene ENSG00000175110.
Subcellular location: Mitochondrion
Subcellular location (Human Protein Atlas): Mitochondria
Pathways (Reactome):
Metabolism of proteins: Mitochondrial ribosome-associated quality control; Mitochondrial translation elongation; Mitochondrial translation initiation; Mitochondrial translation termination
Gene Ontology:
Molecular function: protein binding; structural constituent of ribosome
Biological process: mitochondrial translation
Cellular component: mitochondrial small ribosomal subunit; mitochondrion; mitochondrial inner membrane; mitochondrial ribosome
Genetic constraint (gnomAD): Loss-of-function variants: 28 observed, 41.4 expected, observed/expected ratio (o/e) 0.68, 90% interval 0.5 to 0.93. The upper end of that interval is the gene's LOEUF score, 0.93, which puts it in group 3 of 6, group 1 being the genes least tolerant of losing a copy. Missense variants: 418 observed, 441.58 expected, observed/expected ratio (o/e) 0.95, 90% interval 0.87 to 1.03. Synonymous variants: 154 observed, 154.62 expected, observed/expected ratio (o/e) 1, 90% interval 0.87 to 1.14.
Gene-disease validity (ClinGen):
ClinGen rates the evidence that MRPS22 causes each of these diseases.
mitochondrial disease (autosomal recessive): Definitive.
Homologues: Orthologues: chimpanzee MRPS22 (98% identical), macaque MRPS22 (95% identical), dog MRPS22 (84% identical), rabbit MRPS22 (83% identical), pig MRPS22 (80% identical), guinea pig MRPS22 (79% identical), mouse Mrps22 (79% identical), rat Mrps22 (79% identical), zebrafish mrps22 (53% identical), tropical clawed frog mrps22 (52% identical), Drosophila melanogaster mRpS22 (29% identical), Caenorhabditis elegans mrps-22 (28% identical).
Diseases named in the same sentence as MRPS22 in open-access papers:
MRPS22 is named in the same sentence as 17 diseases in open-access papers, as found by Europe PMC text mining. Sharing a sentence is not in itself a finding about the gene and the disease. The quoted sentences say what the papers report.
hypertrophic cardiomyopathy (3 papers, 2021 to 2024). A condition in which the myocardium is hypertrophied without an obvious cause. "mS22 (MRPS22)—The mutation c.509G > A (p.Arg170His) in mS22 was identified in siblings presenting with edema, hypotonia, hypertrophic cardiomyopathy, and perinatal death." (PMID 33917098, 2021). "Two of these genes, MRPS22 and MRPS25, are implicated in human hypertrophic cardiomyopathy and encephalopathy, although the exact functions of this gene cluster in muscle development need further study." (PMID 39014195, 2024).
colon cancer (1 paper, 2021). "MRPS22 interacts with mitochondrial topoisomerase IB and increases MPT and tumorigenesis in liver and colon cancer models." (PMID 34885140, 2021).
hydrops fetalis (1 paper, 2026). Hydrops fetalis is a severe and challenging fetal condition usually defined as the excessive accumulation of fetal fluid within the fetal extravascular compartments and body cavities that manifests as edema, pleural and pericardial effusion and ascites. "This case consolidates the antenatal phenotype of severe MRPS22-related disease and highlights the importance of considering mitochondrial disease in the differential diagnosis of congenital anomalies, especially hydrops fetalis and corpus callosum anomalies." (PMID 42040991, 2026).
infertile (1 paper, 2024). "The present findings suggested that MRPS22 may play a potential role in the development of infertile intersex individuals." (PMID 38956513, 2024).
lung carcinoma (1 paper, 2013).
cancer (6 papers, 2013 to 2024). A tumor composed of atypical neoplastic, often pleomorphic cells that invade other tissues. "Consistently, DepMap analysis revealed a strong correlation in gene effect between METTL17 and LRPPRC, MRPS9, MRPS22, and MRPS35, highlighting the significance of METTL17-associated cellular functions in cancer cell survival and ferroptosis defense." (PMID 38377789, 2024). "EPHX2, ACSF2, CYP27A1, ACSS1, and ALDH1L1 showed hypermethylation in several types of human cancer; on the contrary, AKR1B10, POLG2, NDUFB8, ACACB, and MRPS22 consistently showed hypomethylation in several types of human cancer." (PMID 37223030, 2023). "Prognostic genes include LAS1L, SUPT4H1, FAM72A, C11orf31 and MRPS22, which play key roles in the biological mechanisms of cancer." (PMID 33976726, 2021). "Then, choosing MRPL11 (UL11m) that was previously evaluated in cancer cells and MRPS22 (mS22) as representatives of the large and small mitoribosome subunits, we observed that the DHX30-depleted cells showed reduced expression of these two genes at both the RNA and protein levels." (PMID 34503222, 2021).
mitochondrial disease (4 papers, 2011 to 2026). "MRPS22-related mitochondrial disease (MIM#611719) is a rare autosomal recessive disorder caused by defects in the mitochondrial ribosomal protein S22, a component of the small mitoribosomal subunit essential for mitochondrial translation." (PMID 42040991, 2026). "We describe a fetus with severe antenatal-onset MRPS22-related mitochondrial disease and the use of multi-omics in the molecular diagnosis." (PMID 42040991, 2026). "Mitochondrial disease-causing mutations were found in thirteen small ribosomal subunit mitoribosomal proteins (MRPS1, MRPS2, MRPS6, MRPS7, MRPS9, MRPS11, MRPS14, MRPS16; MRPS22, MRPS23, MRPS25, MRPS34, MRPS39) and four large ribosomal mitochondrial proteins (MRPL3, MRPL12, MRPL24, MRPL44)." (PMID 36140315, 2022).
cardiac disease (2 papers, 2023 to 2025). "For example, decreased expression of the following proteins has been linked to the development of heart disease: mitochondrial ribosomal protein S3 (MRPS3), mitochondrial ribosomal protein S22 (MRPS22), mitochondrial ribosomal protein 10 (MRP10), and mitochondrial ribosomal protein S44 (MRPS44)." (PMID 40734976, 2025).
MRPS22 also shares sentences with these, for which no sentence is quoted: cardiomyopathy (3 papers); chronic kidney disease (1); Encephalopathy (1); glycogen storage diseases (1); kidney disease (1); male pattern baldness (1); neuroblastoma (1); Obesity (1); sterility (1).